LGALS9 (galectin 9)
Diseases named in the same sentence as LGALS9 in open-access papers (continued):
Sharing a sentence is not in itself a finding about the gene and the disease.
ovarian carcinoma (13 papers, 2013 to 2024). A malignant neoplasm originating from the surface ovarian epithelium. "LGALS1, LGALS3, LGALS4, LGALS8 and LGALS9 were found to be overexpressed in ovarian cancer patients." (PMID 37238197, 2023). "Galectin-9 has been considered in a recent meta-analysis study as prognostic marker indicating poor overall survival rate in epithelial ovarian cancers." (PMID 36050693, 2022). "LGALS1, LGALS3, LGALS4, LGALS8, and LGALS9 were found to be mostly overexpressed in ovarian carcinoma patients with the following percentage: 78.6%, 92.9%, 66.1%, 87.5%, and 85.7% respectively." (PMID 36050693, 2022). "MSLN was positively correlated with immunosuppressive genes in ovarian cancer, such as LGALS9, CD276, TMIGD2, CD200, TNFRSF14, and human leukocyte antigen (HLA)-related families including HLA-DRA, HLA-DRB1, HLA-DPA1, HLA-DMA, HLA-E, etc.." (PMID 35692779, 2022). "For Gal-9 (human Gal-9 gene, LGALS9), out of 12 ovarian cancer patients, 3 showed medium Gal-9 expression and 5 patients showed low Gal-9 expression." (PMID 29361803, 2018). "In the present study, the mRNA expression of five galectins (LGALS1, LGALS3, LGALS4, LGALS8, and LGALS9) is explored in the tumor samples of 56 ovarian carcinoma patients, and the expression fold change was calculated in comparison to 26 adult females with normal ovaries." (PMID 36050693, 2022). "Staining for galectin-9 was assessed in 147 ovarian cancer samples using IR scores." (PMID 29361803, 2018). "The roles of Lgals9, MMP9, and E-cadherin in epithelial ovarian cancer were investigated by immunohistochemical assays and qRT-PCR detection." (PMID 38992056, 2024). "We did not detect any expression of TIM-3 and CD137 molecules and their respective ligands Galectin-9 and CD137L on the surface of ID8 ovarian cancer cells (data not shown), excluding the possibility that inhibition of ID8 tumor growth in vivo is directly mediated by anti-TIM-3 or anti-CD137 mAb." (PMID 24044888, 2013).
atherosclerosis (11 papers, 2015 to 2025). A disease characterized by the build-up of fatty material and calcium deposition in the arterial wall resulting in partial or complete occlusion of the arterial lumen. "As early as 2015, a study demonstrated that serum LGALS9 was associated with the degree of coronary artery stenosis and inhibited the development of atherosclerosis in Chinese." (PMID 39234566, 2024). "During atherosclerosis, galectin-9 modulates inflammation through the activation of T cells, monocytes, and macrophages." (PMID 36873388, 2023). "Further researches are needed to investigate the precise effect of galectin-9 in the process of atherosclerosis." (PMID 33250901, 2020). "One would expect beneficial effects of galectin-9 inhibition in atherosclerosis." (PMID 36873388, 2023).
atopic dermatitis (11 papers, 2013 to 2025). "A similar diet also increased galectin-9 levels in serum of infants affected with atopic dermatitis, in association with reduced skin symptom scores." (PMID 31427886, 2019). "In addition, in children affected with atopic dermatitis, this synbiotic mixture was found to enhance serum galectin-9 levels after 12 weeks of intervention, in association with reduced atopic dermatitis symptom scores and lower risks of developing asthma." (PMID 35327576, 2022). "In addition, increased serum galectin-9 levels upon dietary supplementation with scGOS/lcFOS and Bifidobacterium breve M16V were associated with the prevention of asthma-like symptoms in infants affected with atopic dermatitis." (PMID 31427886, 2019). "Atopic dermatitis (AD), a common type 2 inflammatory disease, is driven by T helper (TH) 2/TH22polarization and cytokines.Galectin-9 (Gal-9), via its receptor T cell immunoglobulin- and mucin-domain-containing molecule-3 (TIM-3), can promote TH2/TH22 immunity." (PMID 35967337, 2022). "Furthermore, in infants with atopic dermatitis, formula milk containing NDO was capable of enhancing serum galectin-9 levels in association with symptom reduction, which supports the translational value of the HT-29 transwell co-culture model to the human situation." (PMID 32438601, 2020).
chronic hepatitis B (11 papers, 2012 to 2025). "In the liver tissues of chronic hepatitis B patients, the expression of LGALS9 is upregulated during the immunologically active and hyperinflammatory phases." (PMID 40708539, 2025). "We investigated whether galectin-9/Tim-3 interactions contribute to the deletion and exhaustion of the antiviral T cell response in chronic hepatitis B virus infection (CHB)." (PMID 23112829, 2012). "Regarding chronic hepatitis B and C, it will be useful to detemine whether galectin-9 abundance correlates with disease severity and correlates with the risk of hepatocarcinoma." (PMID 22805533, 2012). "Indeed, liver biopsies from chronic hepatitis B patients had a high intensity of galectin-9 and CD68 staining that correlated with serum galectin-9 levels and high ALT levels (>100 U/L), indicative of active infection." (PMID 29033936, 2017).
chronic kidney disease (11 papers, 2013 to 2024). Impairment of the renal function secondary to chronic kidney damage persisting for three or more months. "Notably, individuals with type 2 diabetes and chronic renal failure exhibit elevated serum concentrations of galectin-9." (PMID 39583850, 2024). "Furthermore, our bioinformatic analysis results demonstrated a significant lupus nephritis-specific high-expression of LGALS9 in macrophages, as compared to macrophages from IgA nephropathy, allograft biopsy specimen, acute kidney injury and chronic kidney disease." (PMID 38610007, 2024). "This suggests that the increase in serum galectin-9 levels in T2DM patients is closely related to eGFR and may be associated with changes in the immune response and inflammation in patients with T2DM and chronic kidney disease." (PMID 37189444, 2023).
Obesity (11 papers, 2017 to 2025). Accumulation of substantial excess body fat. "Samples from patients with obesity had significantly higher levels of the short isoform of the LGALS9 mRNA compared to samples from lean patients with B-ALL." (PMID 35241678, 2022). "Herein, we aimed to investigate the expression of TIM3 and galectin-9 in peripheral blood and to evaluate their clinical significance in patients with obesity and obesity-related T2DM." (PMID 33123595, 2020). "The level of galectin-9 in the plasma of obesity patients was significantly lower than that of healthy donors and obesity-related T2DM patients." (PMID 33123595, 2020). "In this study, we examined the expression of TIM3 and galectin-9 in the peripheral blood of patients with obesity and obesity-related T2DM to evaluate its role in the pathogenesis of obesity-related T2DM." (PMID 33123595, 2020). "In our study, plasma galectin-9 levels in patients with obesity comorbid type 2 diabetes significantly increased and positively correlated with weight, BMI, hipline, UA, and especially islet-related indicators insulin and C-peptides." (PMID 33123595, 2020). "Galectin-9 is also expressed in adipose tissues, and in diet-induced obesity in mice, subcutaneous adipose tissue showed increased galectin-9 expression." (PMID 29950926, 2018). "In 3T3-L1 adipocytes, we evaluated the effect of organotins on the expression of inflammatory response-related genes such as Lgals9, Fn1, Dcn, Vcam1 and S100a8, which are accordingly related to obesity and insulin resistance." (PMID 28824431, 2017). "Our results suggested that TIM3 and galectin-9 may be potential biomarkers related to the pathogenesis of obesity-related T2DM." (PMID 33123595, 2020). "Finally, the distinct mechanism of the TIM3/galectin-9 pathway in the pathogenesis of obesity-related diabetes should be further explored." (PMID 33123595, 2020). "Our data suggest that the TIM3/galectin-9 pathway might participate in the proceeding from obesity to T2DM, but the exact role of TIM3 in obesity-related T2DM needs to be further elucidated." (PMID 33123595, 2020). "Therefore, in the present study, we evaluated the expression of TIM3 and galectin-9 in peripheral blood among healthy donors, patients with obesity, and obesity patients with newly diagnosed type 2 diabetes." (PMID 33123595, 2020). "But during the progression from obesity to diabetes, galectin-9 could upregulate and trigger phosphorylation of Tyr256 and Tyr263 by the tyrosine kinase ITK, thereby allowing TIM3 to exert the inhibitory function." (PMID 33123595, 2020). "Galectin-9 could aid in clinical decision-making in obesity-related T2DM." (PMID 33123595, 2020). "However, it is still unclear whether the TIM3/galectin-9 signal is involved in the pathogenesis of obesity progression to type 2 diabetes." (PMID 33123595, 2020). "Thus, we hypothesized that TIM3 was constitutively expressed on peripheral T cells at a certain level, and as soon as obesity occurred, galectin-9 could be downregulated." (PMID 33123595, 2020). "The concentration of galectin-9 in the serum of obese T2DM subjects was significantly higher than in healthy individuals and in the group with simple obesity." (PMID 37189444, 2023). "Diabetic patients with obesity had higher galectin-9 expression than nondiabetic obese patients." (PMID 33123595, 2020).
chronic lymphocytic leukemia (10 papers, 2021 to 2025). "Galectin-9 (Gal-9), very poorly characterized in chronic lymphocytic leukemia (CLL), was chosen in our study to examine its potential role as a CLL biomarker." (PMID 38001630, 2023).
HIV-1 infection (10 papers, 2012 to 2024). The type species of lentivirus and the etiologic agent of acquired immunodeficiency syndrome (AIDS). "Galectin-9 (LGALS9) is rapidly released during acute HIV-1 infection." (PMID 27344170, 2016). "Whether HIV-1 infection modulates the expression of Tim-3 on NK cells, or the levels of its ligand Galectin-9 (Gal-9), and how signaling through these molecules affects the NK cell response to HIV-1 remains inadequately understood." (PMID 23866914, 2013). "Galectin-9 mediates HIV-1 transcription and latency reversal in vitro and ex vivo, as well as enhances T-cell migration and HIV-1 infection of T cells via PDI." (PMID 39822268, 2024). "The interaction between galectin-9 and TIM3 expressed on the surface of activated CD4+ T cells induce resistance of activated CD4+ T cells to HIV-1 infection and replication." (PMID 34671358, 2021). "It was recently reported that galectin-9 binds to and increases the retention of PDI on the cell surface, thus facilitating Th2 lymphocyte migration and HIV-1 infection most likely through modulation of the cell surface redox environment." (PMID 23206338, 2012). "Moreover, certain ‘common ISGs’ that were upregulated by HIV-1 infection (IRF7, TRIM25, MYD88, MX2, LGALS9, and SP100) exhibited a strong anti-HIV-1 effect in THP-1 cells." (PMID 30915053, 2019). "Although galectin-9/TIM-3 interaction was reported to protect human CD4 T cells against HIV-1 infection, to date there are no reports demonstrating a specific binding of human galectin-9 to human TIM-3." (PMID 23555261, 2013).
influenza (10 papers, 2014 to 2024). An acute viral infection of the respiratory tract, occurring in isolated cases, in epidemics, or in pandemics; it is caused by serologically different strains of viruses (influenzaviruses) designated A, B, and C, has a 3-day incubation period, and usually lasts for 3 to 10 days. "Specifically, binding of galectin-9 to TIM-3 is thought to have strong suppressive effects on effector T cells, and inhibition of this axis boosted antiviral responses in an influenza mouse model." (PMID 35660785, 2022).
AIDS (9 papers, 2020 to 2024). A syndrome resulting from the acquired deficiency of cellular immunity caused by the human immunodeficiency virus (HIV). "We also did not follow up with these patients to assess the occurrence of non-AIDS events in them and to determine their association with galectin-9 levels." (PMID 37569647, 2023). "Apart from inducing HIV reactivation, galectin-9 levels have also been associated with occurrence of non-AIDS events in HIV-infected individuals." (PMID 37569647, 2023). "Both cystatin C and galectin-9 have been shown to be associated with various non-AIDS adverse events in persons with chronic HIV during suppressive antiretroviral therapy." (PMID 37569647, 2023). "In a study on AIDS, LGALS9 levels were found to predict the probability of myocardial infarction or stroke after receiving antiretroviral therapy." (PMID 39234566, 2024). "Recent measures of specific full-length and cleaved galectin-9 forms showed that AIDS was mainly characterized by a specific increase in the cleaved form of plasma galectin-9, although the full-length form was also significantly increased." (PMID 39822268, 2024). "In relation to HIV infection, plasma galectin-9 levels also appeared to predict onset of AIDS and death within 12 weeks in HIV-infected patients." (PMID 39822268, 2024). "Levels of both cystatin C and galectin-9 correlating with duration of ART suggest a need for screening PLHIV on long-term ART for non-AIDS events." (PMID 37569647, 2023). "Multiple mechanisms are involved in the development of AIDS-related as well as non-AIDS events, apart from galectin-9." (PMID 37569647, 2023). "Cleaved galectin-9 has been shown to be a better biomarker of inflammation and severity in AIDS than the full-length protein." (PMID 37569647, 2023). "Plasma levels of matricellular proteins, such as osteopontin (OPN) and galectin-9 (Gal-9), are known to be elevated in AIDS and TB." (PMID 33143141, 2020). "In ART-treated patients, plasma galectin 9 was a predictor of adverse non-AIDS events." (PMID 39822268, 2024). "The correlation of galectin-9 levels with other parameters like cystatin C levels and blood pressure was also analyzed in a subset of aviremic individuals on long-term ART to determine their association with factors contributing to non-AIDS events." (PMID 37569647, 2023). "Hence, we planned a study to assess plasma galectin-9 levels in PLHIV on ART and their associations with plasma viral load, cystatin C levels, and other parameters possibly contributing to non-AIDS events." (PMID 37569647, 2023). "In addition, our study also indicated a putative role for novel mediators of HIV-1 immunity, namely ZBP1, LAMP3, CXCL10, LGALS9, and ANKYF1, all of which have been associated with HIV-1/AIDS disease progression." (PMID 35333911, 2022). "Strategies for countering the effects of galectin-9 for controlling HIV viremia and non-AIDS events are urgently warranted." (PMID 37569647, 2023). "The results also warrant an urgent need to investigate inhibitors of galectin-9 to counter its effects of contributing to HIV viremia and non-AIDS events." (PMID 37569647, 2023). "The combined effect of galectin-9 and cystatin C on HIV replication impacting HIV viremia and of its contribution to the development of non-AIDS events through inflammaging needs to be explored further." (PMID 37569647, 2023). "Galectin-9, an immunomodulatory protein, is shown to induce HIV reactivation as well as contribute to non-AIDS- and AIDS-defining events." (PMID 36569879, 2022).
diabetes (9 papers, 2012 to 2024). "In mice, galectin-9, upregulated by injection of plasmid encoding galectin-9, inhibits the development of diabetes." (PMID 29950926, 2018). "Other examples include galectin-1 which binds the ganglioside GM-1 in effector T-cells causing autoimmune suppression and galectin-9 which attenuates Th1 responses and is protective against diabetes in the NOD T1D mouse model." (PMID 22685601, 2012). "In another mouse study, injection of galectin-9 inhibited development of diabetes, and an antibody against TIM3 was at least as effective as galectin-9 injections in protecting against development of diabetes." (PMID 29950926, 2018). "Hence, additional studies on galectin-9 and diabetes are needed to see if injection of galectin-9 can prevent diabetes also in human and if the side effects are acceptable." (PMID 29950926, 2018). "For galectin-1 and galectin-9, an increase in the levels of the proteins could protect against diabetes, whilst for galectin-12 inhibition of the protein could be protective." (PMID 29950926, 2018). "Galectin-9 could thus be a possible target for therapeutic strategies to reduce inflammation in obese atients to reduce diseases such as diabetes and fatty liver." (PMID 29950926, 2018). "Interestingly, upregulation of galectin-9 by injection of a galectin-9 plasmid in mice significantly protected them from diabetes." (PMID 29950926, 2018). "Galectin-9 may serve as a potential marker for diabetes initiation." (PMID 33123595, 2020). "Therefore, galectin-9 control of CD40 signals in CD4loCD40+ T cells could be one mode of action for galectin-9 to be protective against diabetes as was demonstrated." (PMID 22685601, 2012). "This strongly suggests that galectin-9 and molecules interacting with it such as TIM3 have key roles in diabetes and have a therapeutic potential." (PMID 29950926, 2018).
endometriosis (9 papers, 2020 to 2025). The growth of functional endometrial tissue in anatomic sites outside the uterine body. "Firstly, we conducted the examination of the dendritic cells with Galectin-9 expression in the systemic and local peritoneal environment of patients with endometriosis." (PMID 36983021, 2023). "There were significantly elevated levels of soluble galectin-9 in both minimal/mild stages of endometriosis (stages I-II) and in moderate/severe stages of endometriosis (stages III-IV) in comparison to the negative controls." (PMID 32033052, 2020). "Potential use of serum galectin-9 as a biomarker for the detection of endometriosis and other gynecological disorders is under consideration." (PMID 32033052, 2020). "In addition to the elevated levels of galectin-9 in women with endometriosis, increased serum galectin-9 levels were also found in women with varying benign gynecologic disorders, pelvic pain, and infertility." (PMID 32033052, 2020). "The potential of soluble galectin-9 as a diagnostic biomarker is particularly significant because it can be detected without laparoscopic diagnostic surgery, a standard way endometriosis and other gynecologic disorders are currently being diagnosed." (PMID 32033052, 2020). "Despite significant advances in the field of the immunological aspects of endometriosis, little is known about the role of the T cell immunoglobulin and mucin domain-containing protein/galectin-9 (TIM-3/Gal-9) pathway in this disease." (PMID 36983021, 2023).